SKP2 (S-phase kinase associated protein 2)
Diseases named in the same sentence as SKP2 in open-access papers (continued):
Sharing a sentence is not in itself a finding about the gene and the disease.
cancer (continued). "Our findings thus add bortezomib to the growing list of anticancer compounds that target the SKP2–p27KIP1 axis to inhibit the growth and survival of many cancers." (PMID 26956626, 2016). "Currently, the search for specific E3 inhibitors (e.g., MDM2, IAP, and SKP2) is a promising strategy for chemotherapy or the prevention of cancer." (PMID 27791197, 2016). "The results of this study also showed patients with high expression of SKP2 (> 10.1% nuclear stain) had higher recurrence of cancer after radiotherapy, especially locoregional recurrence." (PMID 27317767, 2016). "The stability of p27Kip1 is regulated by the E3 ubiquitin ligase SKP2, and RA stabilises p27Kip1 by enhancing the proteasome-mediated degradation of SKP2 in a number of cancer cell lines." (PMID 26902400, 2016). "In particular, overexpression of SKP2, a prominent member of the SCF complex, is ubiquitous in cancer and often associated with tumor biological aggressiveness." (PMID 25537506, 2015). "Skp2 is overexpressed in human cancers and is able to promote degradation of p27 and activation of Akt, leading to cancer initiation and progression." (PMID 26474281, 2015). "Next, we investigated in SKP2/N-RasV12 lesions the levels of tumor suppressors that have been shown to be inactivated in cancer via SKP2-dependent proteolysis, including p27, p57, Dusp1, and Rassf1A, by immunohistochemistry." (PMID 25537506, 2015). "Several prominent F-box substrate receptors of CRL1, such as Skp2, β-TrCP, Fbw7 and Fbxl3, were shown to play significant roles in cancer and other diseases." (PMID 25886174, 2015). "Emerging evidence revealed that SKP2 plays an essential role in cell cycle proliferation, cellular senescence, cancer progression, and metastasis." (PMID 25596733, 2015). "Skp2 is an oncogene that has been shown to be an independent marker for poor prognosis in several types of human cancer." (PMID 25605247, 2015). "Our findings are in harmony with previous reports that SKP2 has a critical pro-oncogenic function for the development and progression of cancers including PCa, through affiliating oncogenic signaling pathways such as RhoA, c-Myc and Ras." (PMID 25596733, 2015). "The elevation of SKP2 protein was found in both cytoplasm and nucleus, while H3K4me3 was primarily accumulated in the nucleus of cancer cells." (PMID 25596733, 2015). "It will be worthy to evaluate if the dysregulation of H3K4 trimethylation depends on Skp2 in other mouse models of cancers, and furthermore the relevance in mTOR signaling pathway." (PMID 25596733, 2015). "Compound #25 binds Skp2 and prevents Skp2-Skp1 interaction, leading to the inhibition of Skp2 activity and suppression of cancer stem cells." (PMID 26474281, 2015). "This group further identified that inhibition of Skp2-SCF ubiquitin ligase restricts cancer stem cell traits and cancer progression." (PMID 26046466, 2015). "In particular, S-phase kinase-associated protein 2 (SKP2), a main member of the SCF complex, is almost ubiquitously overexpressed in cancer and considered to be a bona fide oncogene due to its transforming abilities in vitro and in vivo." (PMID 25537506, 2015). "The target analysis of miR-202 in HeLa cells revealed two interesting targets, -DICER1 and SKP2, with potential importance in cancer." (PMID 26020509, 2015). "Under the conditions that the quiescent cancer cells were allowed to re-enter the cell cycle, Efipladib suppressed a recovery of Skp2 from a low levels seen in the quiescent state." (PMID 26416244, 2015). "Here, we have shown that FKA effectively down-regulated Skp2 protein levels with corresponding accumulation of p27/Kip1 in all tested cancer cell lines regardless their genetic background and in vivo in the prostate of the TRAMP mice." (PMID 26497688, 2015). "Tissue-specific over-expression of Skp2 in prostate promotes proliferation, hyperplasia, dysplasia, and low-grade carcinoma in the prostate gland." (PMID 25788262, 2015).
cancer (continued). "The metastatic cancer cells from high-grade OSC had the highest SKP2, cyclin E, and stathmin staining indexes and borderline serous cystadenoma had the lowest." (PMID 25106448, 2014). "Previous studies have shown that antisense oligonucleotides against SKP2 mRNA inhibited the proliferation of cancer cell lines and increased the sensitivity of these cells to apoptotic stimuli." (PMID 25530715, 2014). "This inhibitor selectively suppresses Skp2 E3 ligase activity, exhibits antitumor function in multiple animal models and reduces cancer survival combining with other chemotherapeutics." (PMID 25015320, 2014). "The protein expression of SKP2, a viable therapeutic target in human cancer, was also reduced by ezetimibe." (PMID 25310357, 2014). "SKP2 alterations have also been found to be key mediators that are involved in cancer growth and drug resistance." (PMID 25530715, 2014). "In agreement with these genetic findings, the specific Skp2 inhibitor against its E3 ligase activity, compound 25, downregulates Akt phosphorylation and represses tumor growth in pre-existing cancer xenografts." (PMID 25309720, 2014). "Skp2 is involved in cell cycle progression, metabolism, metastasis and senescence and was shown to be deregulated in a number of cancers." (PMID 25237759, 2014). "Akt-mediated phosphorylation of Skp2 stabilizes and activates Skp2 and facilitates its cytosolic translocation, thereby promoting cell migration and cancer metastasis." (PMID 25309720, 2014). "Previous reports have demonstrated in various types of cancer, that SKP2 mRNA or protein expression is increased compared with normal tissues." (PMID 25310357, 2014). "In summary, we demonstrated a reciprocal regulation between DAB2IP, a tumor suppressor, and Skp2, an oncogenic protein, in normal prostatic epithelia and PCa cells, which represents paradigm shift of signalosome pattern in normal cell to malignant tumor." (PMID 25115390, 2014). "Studies have shown that SKP2 overexpression was positively correlated with the histological grade of malignant carcinomas." (PMID 25106448, 2014). "Cks1 is also highly overexpressed in the majority of different cancer subtypes afflicting the gastrointestinal system and in most cases is strongly correlated to increased Skp2 expression and reduced p27Kip1 expression." (PMID 24563807, 2013). "Skp2 has been demonstrated to display an oncogenic function since its overexpression has been observed in many human cancers." (PMID 23497154, 2013). "In summary, our data indicated that Tyr-342F phosphorylation of FOXP3 is involved in the inhibitory regulation of cancer malignancy by SKP2, VEGF-A, and MMP9 expression." (PMID 24155921, 2013). "This identified many genes, including CylinD1/D3, Cdk1/2, Psme3, Rad52/54L and Skp2 that have previously been shown to be dysregulated in cancer." (PMID 23762407, 2013). "In human cancers, it was demonstrated that Skp2 overexpression stimulates the degradation of p27, indicating that Skp2 overexpression facilitates accelerated tumor growth and malignant potential." (PMID 23255047, 2013). "Skp2 has also been demonstrated to display an oncogenic function since its overexpression has been observed in many human cancers." (PMID 23497154, 2013). "The c-Myc–Skp2–Miz1 transcriptional complex has been found to activate RhoA gene and to be critical for cell invasion and cancer metastasis." (PMID 22235332, 2012). "Our data from in vitro experiments, including cell proliferation and colony formation, provided evidence for Skp2’s role in facilitating cancer progression, consistent with the survival analysis results of ESCC patients." (PMID 22533738, 2012).
cancer (continued). "In this context, this study sheds light onto a distinct regulatory mechanism between these two F-box proteins in Skp2-overexpressing cancer cells in response to glucose inhibitors." (PMID 23071779, 2012). "This Csn5 downregulation is noteworthy considering the oncogenic role of Csn5 in promoting malignant transformation and progression in many types of cancer, which is, in part, attributable to upregulating Skp2 expression." (PMID 23071779, 2012). "Since Skp2 overexpression can drive T-cell tumorigenesis or other cancers we also widened the quest for oncogenic activity of Cks1 by ubiquitously expressing Cks1 in hematopoetic progenitors." (PMID 22624029, 2012). "Increased levels of Skp2 and reduced levels of p27 occur in various types of cancer, such as gastric carcinoma, prostate cancer, oral squamous cell carcinoma, and diffuse large B-cell lymphoma." (PMID 23300741, 2012). "As Skp2 is often activated in human cancers to increase cell proliferation through genetic amplification and/or upregulated PI3K/Akt signaling, the dynamics of Skp2 and β-TrCP interactions is distinct in cancer cells to maintain protein homeostasis." (PMID 23071779, 2012). "We selected the overlapped genes-PLK1, MCM2, MCM3, MCM7, MCM10 (ranked 13 by NGP-NR in NSCLC patient datasets) and SKP2 to investigate their functions in cancer." (PMID 22838965, 2012). "From a mechanistic perspective, the ability to activate β-TrCP-mediated proteolysis through Skp2 downregulation represents a major pathway by which ERMAs suppress cancer cell proliferation." (PMID 23071779, 2012). "The c-Myc–Skp2–Miz1 transcriptional complex has been previously shown to activate RhoA and to be essential for cell invasion and cancer metastasis." (PMID 22235332, 2012). "These controversies suggest that more studies are warranted for further assessment of the role of Skp2 in cancer progression." (PMID 22533738, 2012). "Overexpression of SKP2 can drive quiescent cells to enter the cell cycle, and promote adhesion-independent growth of cancer cells." (PMID 23226679, 2012). "Over the past decade, SKP2 has emerged as a novel and attractive pharmacological target in cancer therapeutics." (PMID 23226679, 2012). "As β-TrCP promotes the degradation of many cell cycle- and proliferation-related proteins, the ability of Skp2 to suppress β-TrCP proteolysis bestows a growth advantage on these cancer cells." (PMID 23071779, 2012). "Increased levels of Skp2 and reduced levels of p27 are observed in many types of cancer, and these levels are used as independent prognostic markers in several cases." (PMID 21386910, 2011). "Now, considerable studies focus on the therapeutic potential of p27 kip1 and Skp-2 on cancers or vascular diseases." (PMID 21182801, 2010). "Considerable evidence suggests, however, that SKP2 is the prominent regulator of p27 levels in cancer cells." (PMID 21182779, 2010). "It is important to further elucidate the novel substrates for cytoplasmic Skp2, which will provide important insight for developing new anti-cancer treatments." (PMID 19549334, 2009). "We would argue that any direct role in differentiation must be explained to understand the full impact of skp2 upregulation in cancer." (PMID 18081928, 2007). "One characteristic of cancer cells is inappropriate division, and indeed a variety of tumour cells have elevated skp2 levels." (PMID 18081928, 2007). "Regulation of p27 in human cancers is predominantly through a mechanism involving Skp2-mediated proteosomal degradation of p27." (PMID 17088910, 2006). "Skp2 is the ubiquitin ligase subunit that targets p27 for degradation and is the major determinant of p27 deregulation in cancer." (PMID 16859513, 2006). "The important role of Skp2 in controlling p27Kip1 levels in some human cancers, including breast, prostate, colorectal, and oral squamous cell carcinomas, was recently emphasized." (PMID 16168119, 2005).
cancer (continued). "In this tumor sample, cancer cells show strong nuclear staining for Cks1 and Skp2 and weak staining for p27Kip1, but high p27Kip1 staining and low Cks1 and Skp2 staining in the normal surrounding breast tissue." (PMID 16168119, 2005). "Recent studies from our and other laboratories have investigated the expression of Cks1 levels in different human cancers and its relation to Skp2 and p27Kip1 expression." (PMID 16168119, 2005). "SKP2 affects the maintenance and expansion of stem cell pools and regulates pluripotency, which may explain its role in cancer initiation." (PMID 41542047, 2026). "Notably, the ATAD5/PRR11-AS1/SKP2 triplet exhibits favorable prognostic potential across multiple cancers and consistently outperforms individual gene markers in predicting 1-, 3-, and 5-year overall survival." (PMID 42242683, 2026). "As an oncogene, Skp2 is involved in the pathogenesis of various cancers including GBM." (PMID 38341584, 2024). "Therefore, targeting SKP2 increases BM transplantation efficiency and sensitizes the cancer cell or CSC against chemotherapy." (PMID 38559562, 2024). "Thus an overexpression of the Skp2 gene concomitantly decreases the expression level of the p27 gene in diverse cancer types." (PMID 38559562, 2024). "Interestingly, BTZ suppresses the expression of Skp2 and increases the p27Kip1 expression in many types of cancers, and it has also been proven to significantly improve xenograft cancer cells in mice models." (PMID 38559562, 2024). "Inhibiting SKP2 function could stabilize these tumor suppressor proteins and inhibit cancer cell growth." (PMID 37885161, 2024). "We recently showed that the interaction of SKP2 and its substrate p27 enhances OS cancer stemness." (PMID 38355807, 2024). "Taken together, our results suggest that SKP2 inhibitors may reduce the stemness plasticity of OS and should be leveraged as next-generation adjuvants in this cancer." (PMID 38355807, 2024). "While gene amplification may result in an enhanced Skp2 expression in cancers, oncogenic signals could also contribute to its elevated expression." (PMID 38559562, 2024). "The role of SKP2 in cellular processes like cell cycle progression, apoptosis, cellular proliferation, and cellular differentiation makes it a significant player in tumorigenesis and cancer progression." (PMID 37885161, 2024). "Thus, aberrant expression of SKP2 can lead to uncontrolled cell proliferation, a key characteristic of cancer." (PMID 37885161, 2024). "Furthermore, another study on glioblastoma cells also demonstrated that depletion of SKP2 inhibits cancer progression via promoting cellular senescence." (PMID 38559562, 2024). "SKP2, an F‐box protein, is an oncogene and enhances cancer cell growth." (PMID 37885161, 2024). "Also, pharmacological inhibition of Skp2 has been shown to limit cancer stem cell traits and impede cancer progression." (PMID 38561375, 2024).
cancer (continued). "The prognostic significance of SKP2 expression in various cancers was notable, but it was still unclear whether SKP2 could distinguish cancer samples from control samples, which was analyzed in this study." (PMID 37308972, 2023). "We then speculated that SKP2 might also protect Moesin from proteasomal degradation by FBXW2 to facilitate cancer progression." (PMID 37736741, 2023). "Cell experiments have also supported the promotion of SKP2 in cancer progression." (PMID 37308972, 2023). "Various Skp2 inhibiting compounds have been developed to inhibit the degradation of p27 mediated by Skp2 for cancer treatment, such as Skp2E3LIs, and the p27 protein level was taken as a point for selecting Skp2 inhibiting compound, such as when screening SMIP004." (PMID 37089937, 2023). "Therefore, compared with the control tissues, the mRNA expression of SKP2 in most cancers was significantly different." (PMID 37308972, 2023). "Indeed, SKP2 expression is often deregulated in cancer through gene amplification or overexpression and is mainly linked to tumor cell proliferation and stemness." (PMID 38102140, 2023). "SKP2 was highly expressed in 6 cancer types in TCGA and 1 normal tissue in GTEx, and in collected PPIs it could interact with 2257 proteins." (PMID 37845222, 2023). "Additionally, the naturally occurring compounds, Curcumin, lycopene and quercetin exhibit anti‐cancer effects by down‐regulating SKP2 expression leading to cell cycle arrest." (PMID 36881608, 2023). "Developing an Skp2-specific inhibitor with low side effects would benefit cancer therapy." (PMID 37532777, 2023). "Besides, targeting E3 ligase Skp2 attenuates aerobic glycolysis and induces cellular senescence in cancer cells, thereby reducing CSC populations and their function." (PMID 37053008, 2023). "The IC50 data of the Skp2 inhibitors or inhibiting compounds in various kinds of tumors at cellular levels implied that the cancer type, stage and pathological mechanisms should be taken into consideration when selecting Skp2-inhibiting compound for cancer treatment." (PMID 37089937, 2023). "In corroboration, either the genetic or pharmacological targeting of Skp2 has been shown to hit cancer development in diverse genetic tumor models, thus pointing out that the Skp2 factor might represent a potential target for human cancer treatment." (PMID 36769122, 2023). "Consistently, the Skp2 complex controls RhoA transcription, which is crucial for cancer migration." (PMID 37964867, 2023). "In summary, we demonstrate that the Skp2-MLKL axis might contribute to cisplatin resistance through inhibiting cancer cell death in NSCLC." (PMID 37532777, 2023). "This suggests that, except for the regulatory effect of TFs, attention should also be given to other factors that may affect SKP2 expression in specific cancers." (PMID 37308972, 2023). "Thus, this study demonstrates that AKT-Moesin-SKP2 axis can be explored to develop therapeutics for the betterment of cancer intervention." (PMID 37736741, 2023). "More studies are needed to verify the molecular mechanism of SKP2 in various cancers." (PMID 37308972, 2023). "Individuals with cancer of different ages exhibited varying levels of SKP2 expression." (PMID 37308972, 2023). "SMIP004 was reported to induce cancer-cell-selective apoptosis by downregulating Skp2." (PMID 37089937, 2023). "In addition to mRNA level, we evaluated the expression of SKP2 in various cancers and their control tissues at the protein level." (PMID 37308972, 2023). "In addition, in various cancers, SKP2 is differentially (mainly highly) expressed in cancer tissues versus control tissues." (PMID 37308972, 2023). "As depicted, the productions of CDK2 and SKP2 were positively regulated by LEMD1 in cancer cells." (PMID 35286235, 2022). "The depletion of SKP2 restricts cancer stem cell proliferation and survival." (PMID 35874839, 2022). "Similar to Akt, overexpression of Skp2 is detected in many types of human cancers." (PMID 36180910, 2022).